BLOC1S3 (biogenesis of lysosomal organelles complex 1 subunit 3)
Description:
Component of the BLOC-1 complex, a complex that is required for normal biogenesis of lysosome-related organelles (LRO), such as platelet dense granules and melanosomes. In concert with the AP-3 complex, the BLOC-1 complex is required to target membrane protein cargos into vesicles assembled at cell bodies for delivery into neurites and nerve terminals. The BLOC-1 complex, in association with SNARE proteins, is also proposed to be involved in neurite extension. Plays a role in intracellular vesicle trafficking.
Synonyms: BLOS3; HPS8; RP
Tractability: PROTAC: its protein half-life has been measured.
Gene: Protein-coding gene on chromosome 19 (45,178,745 to 45,216,933, forward strand). Ensembl gene ENSG00000189114.
Subcellular location: Cytoplasm
Subcellular location (Human Protein Atlas): Golgi apparatus
Pathways (Reactome):
Vesicle-mediated transport: Golgi Associated Vesicle Biogenesis
Gene Ontology:
Molecular function: protein binding; AP-3 adaptor complex binding; protein transmembrane transporter activity
Biological process: endosome to melanosome transport; eye development; melanosome transport; pigmentation; platelet activation; anterograde axonal transport; anterograde synaptic vesicle transport; melanosome organization; neuron projection development; platelet dense granule organization; protein transmembrane transport
Cellular component: BLOC-1 complex; transport vesicle; cytosol; axon cytoplasm; cytoplasm
Genetic constraint (gnomAD): Loss-of-function variants: 7 observed, 6.21 expected, observed/expected ratio (o/e) 1.13, 90% interval 0.63 to 1.84. That is too few expected variants to judge how well the gene tolerates losing a copy. Missense variants: 307 observed, 249.5 expected, observed/expected ratio (o/e) 1.23, 90% interval 1.12 to 1.35. Synonymous variants: 145 observed, 120.89 expected, observed/expected ratio (o/e) 1.2, 90% interval 1.05 to 1.38.
Gene-disease validity (ClinGen):
ClinGen rates the evidence that BLOC1S3 causes each of these diseases.
Hermansky-Pudlak syndrome 8 (autosomal recessive): Moderate.
Homologues: Orthologues: chimpanzee BLOC1S3 (99% identical), macaque BLOC1S3 (95% identical), dog BLOC1S3 (93% identical), guinea pig BLOC1S3 (89% identical), mouse Bloc1s3 (87% identical), rat Bloc1s3 (87% identical), tropical clawed frog bloc1s3 (36% identical), zebrafish bloc1s3 (35% identical).
Diseases named in the same sentence as BLOC1S3 in open-access papers:
BLOC1S3 is named in the same sentence as 7 diseases in open-access papers, as found by Europe PMC text mining. Sharing a sentence is not in itself a finding about the gene and the disease. The quoted sentences say what the papers report.
oculocutaneous albinism (1 paper, 2021). Oculocutaneous albinism (OCA) describes a group of inherited disorders of melanin biosynthesis characterized by a generalized reduction in pigmentation of hair, skin and eyes and variable ocular findings including nystagmus, reduced visual acuity and photophobia. "Biallelic pathogenic variants in BLOC1S3 cause Hermansky–Pudlak syndrome (OMIM 614077), a sort of incomplete oculocutaneous albinism and platelet dysfunction that includes visual defects." (PMID 33875846, 2021).
schizophrenia (1 paper, 2022). A major psychotic disorder characterized by abnormalities in the perception or expression of reality. "In addition, systematic investigation of BLOC-1 genes in schizophrenia patients revealed a significant association between the BLOC1S3 gene and schizophrenia." (PMID 35815020, 2022).
BLOC1S3 also shares sentences with these, for which no sentence is quoted: albinism (1 paper); cognitive decline (1); infection (1); ovarian carcinoma (1); retinal disorder (1).